METTL14 (methyltransferase 14, N6-adenosine-methyltransferase non-catalytic subunit)
Diseases named in the same sentence as METTL14 in open-access papers (continued):
Sharing a sentence is not in itself a finding about the gene and the disease.
tumor (continued). "Specifically, YTHDF1, IGF2BP2, KIAA1429, RBM15, IGF2BP1, ZC3H13, and METTL3 were significantly up-regulated in tumor tissues by unpaired T-tests (P < 0.05), while ALKBH5, YTHDC2, and METTL14 were significantly down-regulated (P < 0.01)." (PMID 34149792, 2021). "Like the m6A writer proteins METTL3 and METTL14, the m6A reader proteins YTHDF1 and YTHDF2 can act as either an oncogene or a tumor suppressor." (PMID 33922187, 2021). "In summary, our study indicates that METTL14 is the main regulator for the abnormal m6A modification in GC and METTL14 suppresses GC cell progression and aggression by deactivating the PI3K/AKT/mTOR pathway and the EMT pathway as a tumor suppressor." (PMID 33314339, 2021). "As for METTL14, there is also indirect evidence indicating its function in suppressing CD8+ T cell dysfunction and tumor growth." (PMID 34988083, 2021). "However, METTL14 has been identified to be decreased in bladder cancer and related tumor initiating cells (TICs), knockdown of which promotes the cell proliferation, self-renewal, metastasis and tumor initiating capacity through reducing the stability of m6A-modified Notch1 mRNA202." (PMID 33611339, 2021). "It appeared that IGF2BP1/3, ELAVL1, HNRNPA2B1, HNRNPC, KIAA1429, RBM15, LRPPRC, FMR1, YTHDF1/2 are highly expressed in the tumor while FTO, METTL14/16, WTAP, YTHDC1 and ZC3H13 are down-regulated." (PMID 35095993, 2021). "The results showed that the protein expression of METTL14 in OSCC was significantly lower than that in ANCT; the lower the differentiation of tumour cells, the lower the METTL14 expression." (PMID 34900689, 2021). "The expression of m6A regulators with CNV amplification was significantly increased in CC samples compared to normal control samples, such as HNRNPA2B1, IGF2BP1, KIAA1429, and YTHDF1, while METTL14 and YTHDC2 were markedly decreased in the tumor specimens." (PMID 33500720, 2021). "YTHDF1, KIAA1429, HNRNPC, and METTL3 were most significantly upregulated in tumor samples, and METTL16 and METTL14 were markedly downregulated." (PMID 34975871, 2021). "The expression of METTL14, SLC7A11 and COX2 in xenografts tumour sections was further investigated by immunohistochemistry." (PMID 34609072, 2021). "Meanwhile, we found that the expressions of METTL3, METTL14, WTAP, and YTHDF1-3 proteins were significantly lower in the stroma cells than that in the tumor cells." (PMID 34733841, 2021). "Taken together, TIMER analysis indicated that METTL14, ZC3H13, and YTHDC1, as key regulators of m6A modifications, were closely related to tumor immune infiltration in EC." (PMID 34230220, 2021). "In particular, METTL14 interacts with DGCR8 and positively processes pri-miR126 into mature miR126, a typical tumor repressor in HCC metastasis, in an m6A-dependent manner." (PMID 34272618, 2021). "HNRNPC and YTHDF1 were significantly upregulated in tumor tissues compared with corresponding normal tissues, while ZC3H13, YTHDC2 and METTL14 notably decreased." (PMID 34395102, 2021). "CCR5 is widely involved in tumor proliferation and metastasis, and anti-CCR5 therapy has made some progress in various tumors, suggesting that CCR5 and METTL14 play the opposite role in cancer." (PMID 34221955, 2021). "Here, we confirmed the METTL14 was mainly in cell nucleus of the STAD cells, and low METTL14 also correlated to bigger tumor and greater TNM stage, as well as weaker prognosis." (PMID 34476213, 2021). "High METTL14 expression was identified in 64.2% (174/271) of grade I–II tumor tissue and in 28.3% (36/127) of grade III tumor tissue; the between-group difference was highly significant (P < 0.001)." (PMID 33134390, 2020). "Particularly, in contrast to their low CNV frequencies (< 5%) in normal samples, CBLL1, METTL14, RBM15, IGF2BP1, YTHDC1, and YTHDF2 exhibited more than 20% difference in their frequencies of CNVs between tumor and normal samples." (PMID 33585234, 2020).
tumor (continued). "The knockdown of METTL14 reduced the long-term viability, migration, and invasion of BC cell lines (MDA-MB-231, MDA-MB-468, and BT549) and inhibited tumor growth in tumor xenograft models." (PMID 33505967, 2020). "The same situation also exists in METTL14 and FTO, both of which show low expression in tumor tissues." (PMID 32258108, 2020). "Inversely, the expression of METTL14 and HNRNPA2B1 were relatively lower in tumor tissues (p = 0.0016, p = 0.0163 respectively)." (PMID 32219036, 2020). "Five m6A-related genes (ZC3H13, METTL14, YTHDF2, YTHDF3 and HNRNPA2B1) showed significantly downregulated in tumor tissue, while seven regulators (YTHDC2, FTO, WTAP, METTL3, ALKBH5, RBM15 and KIAA1429) was remarkably upregulated in ccRCC." (PMID 32419773, 2020). "In line with this, knockdown of METTL14 in CRC cells resulted in decreased m6A-methylation levels of XIST, leading to elevated XIST levels and enhanced tumor driving effects." (PMID 32111213, 2020). "Those circRNAs can regulate the mRNA of METTL14 as miRNAs sponge and further regulate the expression of PTEN mRNA, a known tumor suppressor gene, by changing its m6A RNA modification level." (PMID 33292652, 2020). "The results showed that the expression levels of seven tRNA-modifying genes (FTSJ1, ADAT1, U13, RNMTL1, TRDMT1, METTL14, and TRMT1L) in NSCLC tumor tissues were significantly lower than that in normal tissues (all P values < 0.05)." (PMID 32393790, 2020). "In this study, we first evaluated the expression of METTL14 in HCC, and the expression of METTL14 in tumor samples was found to be significantly reduced, which is consistent with the findings of a previous study." (PMID 31943856, 2020). "The result further confirmed that both METTL14 and ZC3H13 were significantly down-regulated in the nucleus in tumor tissues relative to normal control, which was consistent with the results of bioinformatics analysis on RNA levels." (PMID 33363011, 2020). "We further investigated the expression and localization of METTL14 in EBV-negative and positive human tumor tissues." (PMID 31226160, 2019). "We supported our co-localization data for METTL14 and EBNA3C in the PTLD tumor tissues with immunofluorescence assays." (PMID 31226160, 2019). "We found that METTL14 and RBM15B mRNA expression significantly decreased, while FTO significantly increased in tumor tissues." (PMID 31159832, 2019). "Consistent with the aggressive tumor progression, mice grafted with PBT707 cells with KD of METTL3 or METTL14 alone or KD of both METTL3 and METTL14 had considerably worse survival outcomes than mice grafted with control GSCs." (PMID 28297667, 2017). "Targeting m6A writers (e.g., METTL3, METTL14), erasers (e.g., FTO, ALKBH5), or circRNA–miRNA interactions could restore regulatory balance and mitigate tumor aggressiveness." (PMID 41516402, 2026). "By analyzing the role of the modification of mRNA and ncRNA in cancer progression, researchers confirmed strong participation, mostly regarding METTL3/METTL14 complex, FTO, and ALKBH5, in tumor cell proliferation, invasion, migration, angiogenesis, metastasis, and drug resistance development." (PMID 41157107, 2025). "Moreover, the overall m6A level and its related METTL3, METTL14, and WTAP protein levels, as well as cytoplasmic MALAT1-exporting IGF2BP3 and its distribution in xenograft tumor tissues, were increased in the HBx group." (PMID 40860202, 2025). "Interestingly, METTL14-mediated m6A-dependent degradation of PDCD1 mRNA reduces PD-1 expression, maintaining CD8+ T-cell activation and restraining tumor growth." (PMID 41164187, 2025). "Furthermore, METTL14 modulates the expression of various chemokines (e.g., CXCL1, CCL2), which promote the expansion of immune-suppressive cells within the tumor microenvironment." (PMID 39911396, 2025).
tumor (continued). "Besides, inhibitors such as RM3 and UZH2 suppress tumor progression in melanoma, AML, and prostate cancer (PCa) by targeting the METTL3/METTL14 complex and reducing m6A modification levels." (PMID 41446042, 2025). "Additionally, METTL14 is involved in regulating TNF‐related genes, IFN‐related pathways in tumors, IL‐6‐induced inflammation, and MHC class I‐mediated tumor immune escape." (PMID 41316520, 2025). "This section highlights METTL14 role in orchestrating TAM behavior, providing evidence that its m6A-mediated regulation contributes to immune suppression and tumor progression, further connecting epitranscriptomic modifications to tumor immunity." (PMID 41164187, 2025). "In addition, the RNA-binding proteins HuR, METTL14/ALKBH5, and their target genes form a feedback loop, regulating each other’s expression in cancer cells and participating in the regulation of tumor occurrence and metabolism." (PMID 39295872, 2024). "In tumor xenograft assays using nude mice, tumor tissue size was measured upon tumor removal, and immunohistochemical analysis indicated that RASAL2-AS1 overexpression promoted HNSCC cell proliferation and growth, while silencing of METTL14 inhibited these effects." (PMID 38528591, 2024). "In addition, the RNA-binding proteins HuR and METTL14/ALKBH5 and their target genes form a feedback loop, regulating each other’s expression in cancer cells and participating in the regulation of tumor occurrence and metabolism." (PMID 39295872, 2024). "Conversely, METTL3 and METTL14 act as tumour suppressors in Triple‐Negative Breast Cancer (TNBC), where their downregulation leads to tumour growth and metastasis." (PMID 38545841, 2024). "Thus, we first examined the expression levels of METTL3, METTL14, WTAP, RBM15, FTO, and ALKBH5 transcripts in tumor samples and corresponding normal samples using the GEPIA database." (PMID 38665783, 2024). "Therefore, METTL14 is a potential biomarker for STAD prognostic and therapeutic targets, and METTL14 agonists have broad clinical applications in tumor therapy." (PMID 39289775, 2024). "In tumor cells, METTL3 and METTL14 can inhibit the expression of CXCL9 and CXCL10." (PMID 39726589, 2024). "Moreover, we found that METTL14 mRNA level and protein level were highly expressed in NPC tumor tissues compared with their respective control groups." (PMID 38956710, 2024). "Additionally, the expression of most of the regulators influences the tumor T feature of KIRC, LIHC, PRAD, STAD and THCA, especially IGF2BP1 in BRCA; IGF2BP2, IGF2BP3, LRPPRC, and METTL14 in KIRC; and IGF2BP3 in KIRP." (PMID 39457524, 2024). "Moreover, METTL14 is remarkably decreased in HCC tissues and acts as a prognostic factor for tumor recurrence in HCC." (PMID 38545555, 2024). "study, which found that METTL3/METTL14 upregulation could enhance OSCC chemoresistance and accelerate tumor growth in vivo." (PMID 38966069, 2024). "The results showed that neither METTL3 nor METTL14 exhibited cytoplasmic localization, and their nuclear localization exhibited substantial deviation, particularly in tumor tissues." (PMID 38965238, 2024). "Furthermore, regulation of the m6A methyltransferase Mettl14 in TAMs can promote CD8+ T cell dysfunction and tumor progression." (PMID 39759516, 2024). "In addition, several studies have reported the potential tumor-promoting or tumor-suppressing effects of m6A methylation-related factors such as METTL3, METTL14 and FTO in PCa." (PMID 37033963, 2023). "KRAS‐WT and KRAS‐MT tumor tissues displayed no obvious differences in METTL14 mRNA levels (Fig EV1F)." (PMID 36794620, 2023). "Abnormal expression of METTL14 has been observed in diverse malignancies, indicating its nonnegligible role in tumor progression." (PMID 36810108, 2023).
tumor (continued). "Through the conjoint analysis of TCGA and GTEx databases, the transcript expression levels of these regulators were all disordered in LUAD tumor tissues (all P < 0.05, except for METTL14), but all differences were not significant (all |log2FC|< 1)." (PMID 37029420, 2023). "Another study demonstrated that METTL14 facilitated global genome repair (GGR) by regulating m6A RNA methylation-mediated DNA damage-binding protein 2 (DDB2) translation and inhibits ultraviolet B- (UVB-) induced skin tumorigenesis." (PMID 37124930, 2023). "On another note, while studies are lacking assessing m6A regulated B cell dysregulation in TIME, B cells in the germinal center of a non-tumor model, are tightly controlled by METTL3 and METTL14, indicating their potential application in potential B cell targeted immunotherapy in the future." (PMID 37015927, 2023). "Up-regulation of LNC942 could significantly promote BRCA cell proliferation, colony formation, metastasis, as well as inhibit apoptosis through METTL14/CXCR4/CYP1B1 signaling pathway axis, and significantly promote tumor growth in mice." (PMID 37901333, 2023). "Because we surprisingly found that both “writers” (METTL3, METTL14 and WTAP) and “erasers” (ALKBH5 and FTO) could abnormally overexpressed and exert oncogenic functions or downregulated and play tumour suppressor roles in urologic tumours." (PMID 37284313, 2023). "METTL14 is rarely expressed in BLC tissues and tumor-initiating cells (TIC) and knocking out METTL14 promotes cell survival, self-renewal, migration, and invasion by regulating Notch1 mRNA stability, which plays an important role in TIC-driven BLC tumorigenesis." (PMID 35864970, 2022). "Therefore, we conclude that m6a-related mRNAs, especially METTL14, IGFBP2, and FTO, can influence the clinical outcome of HCC by altering tumor cell proliferation and survival." (PMID 35734590, 2022). "In addition, a few studies have suggested that certain writers (METTL3, METTL14, and ZC3H13) exert a tumor-suppressing effect." (PMID 35945641, 2022). "One study demonstrated a negative correlation between METTL3 or METTL14 and STAT1 in patients with low mutational tumor burden and tumors associated with the mismatch-repair-proficient or microsatellite instability-low (pMMR-MSI-L) genotypes." (PMID 35885000, 2022). "Also, METTL14 expression correlated negatively with Treg cells in BC, and the METTL14/CCL5/Tregs axis was a potential signaling pathway for regulating anti-tumor immunity in ccRCC." (PMID 35296338, 2022). "In addition, METTL14 mediates stability of PTEN mRNA that negatively regulates the AKT/PKB signaling pathway and exerts a tumor suppressor effect." (PMID 34904301, 2022). "METTL14 and ZC3H13 have been reported to function as tumor suppressors in most cancer." (PMID 35864970, 2022). "In addition, down‐regulation of METTL14 is a detrimental prognostic factor for recurrence‐free survival of HCC and is appreciably related to tumor aggression." (PMID 34904301, 2022). "The results showed that expression levels of METTL3, VIRMA and CBLL1 were significantly increased, while expression levels of METTL14 and ZC3H13 were significantly decreased in HCC, which was closely related to clinicopathological factors, such as tumor stage and prognosis." (PMID 35223847, 2022). "Furthermore, the oncogenic role proposed for METTL14 in BlCa was further supported by in vivo CAM assay, with significantly reduced tumor size and vessel density found in METTL14‐KD cells." (PMID 35048498, 2022). "It has been reported that METTL14 depletion significantly downregulates m6A levels in tumor stromal cells, thereby decreasing CD8+ T cell infiltration and increasing dysfunctional T cells, leading to tumor growth." (PMID 35331234, 2022).
tumor (continued). "Furthermore, upregulation of METTL14 mediates cisplatin resistance through activating the AMPKα/ERK1/2/mTOR pathway to reduce autophagy and apoptosis, resulting in accelerated tumor proliferation and metastasis." (PMID 35794625, 2022). "Besides, the expression of METTL14 and METTL3 at protein level were significantly upregulated in the tumor adjacent tissues." (PMID 36172147, 2022). "For example, METTL14 in TAM promotes dysfunction of CD8+ T cells and tumor progression." (PMID 35794625, 2022). "Decreased m6A level by knockdown of the expression of METTL3 and/or METTL14 or overexpression of the eraser FTO can significantly accelerate tumorigenesis, specifically promoting the growth of human GSCs, as well as their self-renewal and tumor progression." (PMID 34381710, 2021). "Previously, RNA functional analysis confirm that METTL14 and ALKBH5 can regulate the expression of each other, inhibit the demethylation activity of YTHDF3, and induce aberrant m6A modification to play roles in tumour angiogenesis and metastasis." (PMID 35004679, 2021). "METTL3/METTL14-catalyzed m6A methylation and NSUN2-induced m5C methylation can jointly enhance the expression of p21 mRNA in response to oxidative stress-triggered cellular senescence in tumor cells." (PMID 33754077, 2021). "We chose some regulators for RT-qPCR validation, and the qPCR results revealed that METTL3, METTL14, and FTO had consistently low expression in 33 paired samples with TCGA data, while YTHDF1 and YTHDF3 showed increased expression in tumor samples compared to adjacent tissues." (PMID 34804948, 2021). "METTL3-and METTL14-induced dysregulated m6A modification could account for the aberrant expression of LNCAROD and lead to the malignant behaviour of tumour cells." (PMID 35004679, 2021). "Notably, several specific m6A regulators play dual roles in cold tumor formation, such as METTL3, METTL14, and YTHDF1, suggesting the exact role m6A RNA modification-mediated cold tumor formation is tumor-type dependent." (PMID 34616742, 2021). "Since METTL14 is down-regulated and correlated with tumor growth and TNM stage in STAD, an assumption was made that METTL14 could perform the function of tumor suppressor in STAD." (PMID 34476213, 2021). "Unlike METTL3, METTL14 have been demonstrated to show tumor-suppressive functions in most types of cancer." (PMID 33430867, 2021). "While METTL14 and YTHDC2 functioned as tumor suppressors in KIRC." (PMID 33718187, 2021). "In conclusion, the m6A methyltransferases METTL3, METTL14, WTAP, KIAA1429, and METTL4 are dysregulated in ccRCC and might act as tumor suppressor genes." (PMID 35474700, 2021). "However, it seems contradictory for METTL3, METTL14, and WTAP, the three components of the methyltransferase complex, to exhibit different effects on tumor cells." (PMID 33314339, 2021). "The methyltransferases methyltransferase-like 3 (METTL3) and methyltransferase-like 14 (METTL14), which are major responsible proteins for m6A-RNA-methylation, were found to be upregulated in HCC in several studies leading to increased tumor growth both in vitro and in vivo." (PMID 31906510, 2020). "Although both of METTL3 and METTL14 could act as m6A “writer”, METTL3 might promote the progression of CRC, while METTL14 functions as a tumor suppressor in CRC." (PMID 33015074, 2020). "Furthermore, ALKBH5 and METTL14 interact with each other and inhibit YTHDF3 activity, thus accelerating tumor angiogenesis." (PMID 32513173, 2020). "However, recently METTL3 and METTL14 were reported to proliferation and migration of suppress CRC through regulating the p38/ERK pathway and tumor suppressor miR-375, respectively." (PMID 32513173, 2020). "It is worth noting that the expressions of METTL14 and METTL3 in tumor tissues are opposite." (PMID 32258108, 2020). "The overexpression of RBM15B, METTL14, and HNRNPA2B1 is significantly related to tumor metastasis." (PMID 32582536, 2020).